RN7SL236P (RNA, 7SL, cytoplasmic 236, pseudogene)
Gene: Miscellaneous RNA gene on chromosome 17 (78,370,852 to 78,371,135, reverse strand). Ensembl gene ENSG00000243870.
Homologues: Orthologues: chimpanzee Metazoa_SRP (98% identical), macaque Metazoa_SRP (88% identical). Paralogues in human: RN7SL2 (84% identical), RN7SL1 (84% identical), RN7SL3 (83% identical), RN7SL448P (80% identical), RN7SL126P (80% identical), RN7SL444P (80% identical), RN7SL493P (80% identical), RN7SL45P (79% identical), RN7SL586P (79% identical), RN7SL769P (79% identical), RN7SL230P (79% identical), RN7SL652P (79% identical), and 703 more.